PTCH1 (patched 1)
Diseases named in the same sentence as PTCH1 in open-access papers (continued):
Sharing a sentence is not in itself a finding about the gene and the disease.
tumor (continued). "In addition to being a known tumour suppressor, PTCH1 is a receptor for hedgehog ligands, which are involved in proliferation and differentiation during embryogenesis." (PMID 25822509, 2015). "Misregulation of the signaling caused by inactivation of PTCH1 is involved in the development of NBCCS and some related sporadic tumors, supporting the hypothesis that PTCH1 functions as a tumor suppressor gene." (PMID 24204797, 2013). "The tumor with a PTCH1 R571W mutation did not have elevated GLI1 expression, suggesting that this mutation was a passenger rather than a driver." (PMID 24368541, 2013). "Therefore, protein levels were particularly examined for differences between tumor samples from Ptch1+/− Nos2+/+ and Ptch1+/− Nos2−/− mice." (PMID 22438824, 2012). "Using quantitative real-time PCR (qRT-PCR), significant downregulation of the wild-type Ptch1 transcript and upregulation of the Shh target genes Gli1 and N-myc were generally observed in the tumor samples, indicating all examined MBs to be of the same Hh-dependent molecular subtype." (PMID 22438824, 2012). "For an initial assessment of the molecular tumor characteristics, gene expression of hedgehog signaling pathway components were measured in 21 MBs and 24 normal (adult) cerebellar tissue samples from both Ptch1+/− Nos2+/+ and Ptch1+/− Nos2−/− mice." (PMID 22438824, 2012). "The PTCH1 gene, located in chromosome region 9q22, is a candidate tumour-suppressor gene, as loss of heterozygosity on chromosome arm 9q occurs in more than 50% of TCC, and PTCH1 mRNA expression is low, compared with normal urothelium, in early-stage tumours exhibiting LOH in the 9q22 region." (PMID 22361633, 2012). "The examination of tumor-relevant changes in developing cerebellum as a consequence of impaired Nos2 activity and hence NO signaling surprisingly revealed a decreased proliferation of GCPs in the cerebellum of Ptch1+/+ Nos2−/− mice." (PMID 22438824, 2012). "However, we were unable to find any significant correlation between GLI1 and PTCH1 expression in the cell lines and tumor samples (p = 0.07)." (PMID 21059263, 2010). "Further analysis did not reveal association between PTCH1 expression and tumor subtypes, stage or other characteristics." (PMID 19943941, 2009). "Furthermore, a greater histological grade of the tumour was associated with overexpression of GLI1, GLI2, PTCH1 and SMO, which may indicate a critical function for Hh signalling in HNSCC malignancy." (PMID 39234399, 2024). "Particularly mutated PTCH1 may further disinhibit SMO until SHH-independent pathway activation occurs, eventually resulting in cell cycle disruptions, uncontrolled proliferation and ultimately tumor formation." (PMID 39796697, 2024). "In addition, the silencing of miR-17–92 and its orthologue miR-106a–25 clusters by 8-mer LNA-modified antimiR oligonucleotides attenuated tumor growth of PTCH1-driven MBs, indicating that these miR clusters are also important for both tumor initiation and progression." (PMID 35573667, 2022). "However, loss or inactivation of Fbxw7 could have an antitumor or protective effect in Hedgehog-dependent tumors including tumors dependent on inactivating mutations in PTCH1 or activating mutations in SMO, which both require an intact cilium for tumor growth." (PMID 34518642, 2021). "It would be interesting to know whether tumor aggressiveness correlated with the presence or absence of PTCH1 or SMO with FBXW7 mutations." (PMID 34518642, 2021).
tumor (continued). "Mutations affecting proteins involved in HH signaling, including loss of the negative regulator PTCH1 and the activating point mutation in SMO (W535L for human SMO and W539L for mouse Smo), result in hyperactivation of the HH pathway and can lead to cilia-dependent tumor formation in MB." (PMID 34638386, 2021). "Furthermore, additional mutations in PTCH1 (subclonal), PDGFRB, and the NAB2-STAT6 fusion were confirmed as a somatic event in tumor tissue, none of which have reported therapeutic options with clinical benefit in patient’s tumor type." (PMID 34452612, 2021). "In nodules derived from primary Ptch1+/−/Tis21KO MBs, treatment with MEN1611, a novel PI3K inhibitor, causes a dramatic reduction of tumor growth, inhibiting proliferation and, conversely, increasing apoptosis, also of tumor CD15+ stem cells, responsible for long-term relapses." (PMID 34395258, 2021). "Thus, we can speculate that such an increase of CD15+ cells in the Ptch1+/−/Btg1KO model may be ascribed to an activation of existing tumor stem cells—possibly triggered by the high level of apoptosis of tumor cells—followed by their entry into quiescence." (PMID 32231994, 2020). "We therefore quantified the amount of cholesterol in tumor extracts and, indeed, found that tumors treated with iP-sPAH contained significantly more cholesterol than other tumors, indicating that sPAH inhibited cholesterol efflux mediated by Ptch1 in this system." (PMID 32526884, 2020). "Thus, targeting PTCH1-mutant PF cells with a SMO inhibitor resulted in tumor cell death." (PMID 31362756, 2019). "We stratified our patients into three risk groups: 1) High-risk: VSCC associated with LS and showing PTCH1 under-expression; 2) Moderate-risk: a tumour either arising from LS or showing PTCH1 under-expression; 3) Low-risk: tumour neither associated with LS nor showing PTCH1 under-expression." (PMID 30379908, 2018). "However, little was known about the role of PTCH1 in tumor migration and invasion." (PMID 29435142, 2018). "This is not the case in RMS as PTCH1 mutations are not present in these tumours." (PMID 30068568, 2018). "As another example, ctDNA analysis in BR28 showed that EGFR p.R521K and PTCH1 p.T1195S variants were more frequent than ATM pH1380Y, BRCA2 p.N289H, and BRCA2 p.N991D, whereas all these variants were present at a similar frequency in tumor tissue samples at diagnosis and after the 1st NAC cycle." (PMID 29156805, 2017). "Considering the other genes with novel frequent frameshift mutations, BCL9 and PTCH1 mutations were also mostly heterozygous and truncal, although one tumor had a homozygous BCL9 mutation and both genes were found to have a subclonal mutation in one tumor each." (PMID 28539123, 2017). "Besides being the receptor for hh ligands, Ptch1 is a potent tumor suppressor in the skin." (PMID 26413810, 2015). "Mutations in components of this pathway, particularly Patched1 (PTCH1) and Smoothened (SMO), lead to uncontrolled cell proliferation and tumor formation." (PMID 39682631, 2024). "Elevated levels of Gli1 and Sufu in MBs that spontaneously developed in Ptch1–/+ mice prompted us to determine if this was also the case in humans by examining GLI1 and SUFU expression in a tumor tissue array containing 49 unstratified MB specimens." (PMID 38358805, 2024). "Jeng also found that overexpression of PTCH-1 mRNA correlates with the invasive characteristics of HCC, such as higher AFP value, larger size, vascular invasion, and tumor-node-metastasis stage (TNM stage)." (PMID 38730691, 2024). "SHH overexpression was observed in OSCC, whereas expression of PTCH1 and GLI1/2 was noted in the vascular cells in the front of the tumor." (PMID 37626893, 2023).
tumor (continued). "This was the first report that demonstrated a novel PTCH1::GLI2 gene fusion in gastroblastoma, and thus expanded the molecular spectrum of this tumor." (PMID 36147912, 2022). "It is important to emphasize that the effect of Neu1+/− is not in the generation of RMS, but rather in its pleomorphic transformation once the tumor is initiated; while ETV7 expression is promoting a high incidence of RMS formation in Ptch1+/− mice." (PMID 36127469, 2022). "To understand if there is a correlation between circulating Shh levels and the activation of the Hedgehog pathway in HCC, we performed immunostaining on the sections of the tumor tissue for the expression of GLI-1 and PTCH1." (PMID 34692546, 2021). "In both tumour and normal vulval epithelium, expression of SHH ligand was localised to the cytosol; PTCH1 to the membrane, cytosol and nucleus; and GLI1, GLI2 and GLI3 to the cytosol and nucleus." (PMID 34480080, 2021). "However, there are cases where somatic SUFU or PTCH1 variants were identified in tumor DNA but could not be confirmed in the germline." (PMID 34888241, 2021). "However, the findings of tumour cells may not be necessarily applicable to normal cells or syndromic fibroblasts carrying a heterozygous loss of function PTCH1." (PMID 34831015, 2021). "PTCH1 and GLI1 mRNA expression as an indication of the canonical SHH signaling pathway activity in tumor malignancy." (PMID 33391411, 2021). "Blockage of PTCH1 and SMO activity with vismodegib-inhibited tumor growth in both HBx-transgenic mice and HBx-positive human HCC xenograft models." (PMID 33440657, 2021). "Also the tumor latency in double-mutant mice, either Ptch1+/−/Btg1+/− or Ptch1+/−/Btg1KO, did not significantly differ from that of control Ptch1+/−/Btg1WT mice (Ptch1+/−/Btg1+/− vs. Ptch1+/−/Btg1WTp = 0.852; Ptch1+/−/Btg1KO vs. Ptch1+/−/Btg1WTp = 0.386; Student's t-test)." (PMID 32231994, 2020). "PDA tumor cells secrete HH ligands, mainly SHH and indian hedgehog (IHH), which bind to the transmembrane receptor Patched 1 (PTCH1) on fibroblasts." (PMID 33198201, 2020). "Next, we compared the expression levels of various HH target genes (GLI1, PTCH1, and PTCH2) in normal human primary esophageal epithelial cells and EAC cell lines derived from tumor samples." (PMID 32913560, 2020). "Tumor growth was suppressed by treatment with Hh inhibitors, and this inhibitory effect correlated with the downregulation of GLI1 and PTCH1 levels in fibroblasts." (PMID 31658643, 2019). "In contrast to positive expression of PTCH1 and GLI1 in our findings, it is essential to show that tumor cell RNA is preserved and available for hybridization." (PMID 30769952, 2019). "In the tumor, the Hh pathway ligands, SHH and IHH, had undetectable expression consistent with ligand-independent Hh pathway activation following PTCH1 inactivation." (PMID 31362756, 2019). "This paracrine mechanism is characterized by binding of tumor-secreted Hh ligands (SHH, Indian Hedgehog (IHH), or Desert Hedgehog (DHH)) to PTCH1 receptors, and elevated levels of GLI1, GLI2, PTCH1, and SMO genes in the tumor-adjacent stroma." (PMID 31658643, 2019). "PTCH1, SHH, DHH, and GLI1 over-expression were observed in 74%, 95%, 92% and 98% tumour specimens of the cohort." (PMID 29329585, 2018). "IHC staining was undertaken to evaluate the expression of Hh pathway components (SHH, PTCH1 and GLI1) in the primary tumour and their respective adjacent histologically normal epithelium." (PMID 30379908, 2018). "In untreated PDX tumours, SHH and IHH were transcribed predominantly in the human-derived tumour epithelium, while Gli1, Ptch1 and Smo were transcribed predominantly in the murine stroma." (PMID 29715275, 2018).
tumor (continued). "Paired non-parametric comparisons of average tumour expression showed an increase in the expression of SHH ligand (p<0.001), PTCH1 (p<0.001) and cytosolic GLI1 (p = 0.002) in the primary tumour compared to the adjacent histological normal epithelium." (PMID 30379908, 2018). "SHH, DHH, PTCH1 and GLI1 were significantly over-expressed in tumours as compared with respective normal mammary tissues." (PMID 29329585, 2018). "A major strength of our study is that we compared the levels of individual Hh pathway components (SHH, PTCH1, and GLI1) in primary tumours with tumour adjacent normal epithelium." (PMID 30379908, 2018). "A reduction in the tumor mass is partly explained by the decrease in the expression of GLI-1 and PTCH1 when compared to control groups." (PMID 28948003, 2017). "In BR28, for example, relatively high frequencies of EGFR p.R521K and PTCH1 p.T1195S over ATM p.H1380Y, BRCA2 p.N289H, and BRCA2 p.N991D were observed in plasma compared to tumor tissue data, indicating tumor heterogeneity." (PMID 29156805, 2017). "The Hh signaling pathway appeared to be more active in PCa than in benign prostate tissue, as demonstrated by lower expression of the negative regulators PTCH1 and GLI3 in the tumor tissue compared to benign." (PMID 28877722, 2017). "From the tumor material, array-CGH, PTCH1, and SUFU direct sequencing were performed for 13, one, and three cases, respectively." (PMID 26857864, 2016). "In fact, in addition to this CYLD tumor suppressor, several key tumor suppressors and oncogenes such as the VHL, PDGFR-α, and Shh/Patched 1 (Shh/Ptch1) were recently identified to regulate ciliogenesis." (PMID 31093340, 2016). "In another mouse model of MB, in which PTCH1 is inactivated, bortezomib had anti-tumor activity, down-regulated the SHH pathway and restored PTCH1 levels." (PMID 26475605, 2015). "Positive expression of HIF-1α was found in 57.7% of all the tumor samples from all clinical stages, and the degree of positive staining for SHH, PTCH1 and GLI1 was 64.8%, 46.5%, and 54.9%, respectively." (PMID 25811359, 2015). "Since Hh signaling plays a critical role in mammary stem cell maintenance within the mammary epithelium, it is not surprising that mammary CD44+/CD24−/lowLin− CSCs express increased mRNA transcript levels of PTCH1, GLI1 and GLI2 compared to bulk tumour cells." (PMID 26270676, 2015). "Although alterations in SHH pathway genes (e.g.PTCH1, SUFU) are observed in many of these tumours,high throughput genomic analyses have identified few other recurringmutations." (PMID 24252690, 2013). "The PTCH1 promoter region was methylated as assayed by the MCA-MSP method in only 1/8 astrocytic cell lines (CCF-STTG-1 and 3/44 (7%) primary tumor samples." (PMID 21059263, 2010). "The tumor had elevated levels of both Patched 1 and phosphorylated AKT, indicating that both pathways were activated in this tumor." (PMID 19555497, 2009). "All tumor types showed GFP expression and increased Patched 1 levels, suggesting involvement of zebrafish Smoa1 in tumorigenesis." (PMID 19555497, 2009). "PTCH1 (350 Kb downstream to FANCC) is a key regulator in stem cell renewal hedgehog signaling pathway and functions as a tumor suppressor by inhibiting G1-S and G2-M phases of cell cycle." (PMID 18990233, 2008). "PTCH1+/-PTCH2-/- and PTCH1+/-PTCH2+/- animals showed a higher incidence of tumors and a broader spectrum of tumor types compared with PTCH1+/- animals." (PMID 19032739, 2008). "In four common samples where we observe up-regulation of Perlecan in tumor tissue, we previously detected up-regulation of SHH, PTCH1 and GLI1 (patients 945, 1854, 921 and 1866) suggesting a complete functional pathway in these tumors." (PMID 16507112, 2006). "However, the precise role of suppressor of fused (SUFU), one of the two well-recognized tumor suppressor genes in the SHH pathway, in addition to Patched1 (PTCH1), is not completely understood." (PMID 38358805, 2024).
tumor (continued). "In tumor-induced skin, a single treatment with AFL monotherapy resulted in significant mean reductions of mRNA expression of all three hedgehog genes (Gli1, 72.4%, p = 0.003; Gli2, 55.2%, p = 0.010; Ptch1, 70.9, p < 0.001)." (PMID 38308119, 2024). "So, a tumor tissue was only considered a mutant for PTCH1 (for example) if that sample harbored at least one of the non-synonymous SNVs in PTCH1 but not if it harbored only some other SNVs in the PTCH1 gene." (PMID 38920684, 2024). "Advanced HNSCC tumours were shown to express higher levels of SHH, PTCH1, SMO, GLI1, GLI2 and GLI3." (PMID 39234399, 2024). "In NSCLC patients, PTCH1 was underexpressed in the tumor specimens compared with normal lung samples." (PMID 36874015, 2023). "Tumor volume and tumor weight were both reduced compared to the control group in conjunction with reduced cell proliferation and IHC signal expression of SMO, PTCH1, and GLI1." (PMID 36986819, 2023). "In pancreatic cancer, SHh indirectly promotes tumor angiogenesis by inducing Ptch1 and Gli1, thereby inhibiting two enriched stroma-derived antiangiogenic factors (THBS2 and TIMP2), and directly promotes tumor angiogenesis by activating small GTPases of the RHO family in the presence of VEGF." (PMID 36517618, 2022). "However, one PTCH1 variant, P1399S, was present at approximately 0.5 allele frequency in the pre-treatment and recurrent tumor, but not in the post-treatment excision sample suggesting tumor specificity and pathogenicity, although this variant has not yet been described in the literature." (PMID 36455049, 2022). "For the tumorigenesis experiment, Ptch1+/−/C57BL/6 mice of mixed gender were treated with an extended DSS protocol consisting of 5 DSS cycles followed by 14 days of recovery with tap water, to cover the majority of the tumor developmental window." (PMID 36232813, 2022). "Moreover, the CTD of PTCH1 phys(BCC) ically interacts with the ULK complex through ATG101 and impairs autophagic flux as a tumor suppressor." (PMID 35573667, 2022). "The function of the receptor of Hh signalling pathway PTCH1 as a tumour suppressor is not surprising and has already been shown in other studies." (PMID 33713376, 2021). "Furthermore, the BCCs developed in Ptch1+/− models are very heterogeneous, similar to BCC tumor presentation in a clinical setting." (PMID 34944945, 2021). "In contrast, the Hedgehog (Hh) receptor Patched1 (PTCH1) was shown to bind ATG101 through the PTCH1 C-terminal domain and inhibit autophagy flux, which further influences PTCH1-dependent tumor suppression independent of Sonic Hedgehog canonical signaling." (PMID 34502089, 2021). "Interestingly, when LNCaP-AI cells were grown as spheroids, a more biologically relevant model of tumor growth, SHH expression increased while PTCH1 and GLI1 remained unchanged." (PMID 34290270, 2021). "In contrast, these key Hh pathway components were found to be significantly over-expressed in VSCC compared to normal vulval epithelium: SHH (median 1.0), PTCH1 (median 2.0), GLI1 (median 3.5) and GLI2 (median 3.5), and their expression were uniformly distributed across the tumour." (PMID 34480080, 2021). "Additionally, lower expression of PTCH1 was positively correlated with increased nuclear GLI1 in both normal epithelium and tumor samples." (PMID 34572373, 2021). "In MBs developing in Ptch1+/− mice, deletion of Btg1 does not alter tumor and lesion frequencies, nor affect the proliferation of neoplastic precursor cells." (PMID 32231994, 2020). "The identification of Cyclin B1 sequestration by PTCH1 demonstrates a tumor-suppressive function independent of downstream SHH signaling components." (PMID 32957513, 2020). "Furthermore, the expression of PTCH1 and GLI1 was only visible in the tumor cell nucleus in cranial, spinal primary tumors and relapses." (PMID 30769952, 2019).